LGALS3BP (galectin 3 binding protein)
Diseases named in the same sentence as LGALS3BP in open-access papers (continued):
Sharing a sentence is not in itself a finding about the gene and the disease.
ovarian carcinoma (13 papers, 2013 to 2024). A malignant neoplasm originating from the surface ovarian epithelium. "High expression of vesicular LGALS3BP was found to be associated with poor prognosis in ovarian cancer." (PMID 37195369, 2023). "In another study, it was found that LGALS3BP and s-IL-2R (soluble form- Interleukin 2 Receptor) serum levels were associated with poor prognosis in a retrospective study on 152 ovarian-cancer patients before primary surgery." (PMID 34565385, 2021). "The glycoprotein galectin-3 binding protein (LGALS3BP) was identified in cancer-derived EVs for the first time in ovarian cancer." (PMID 39432076, 2024). "In another study, tandem mass spectrometry analysis of the secretome from early-stage 3D ovarian cancer models revealed LGALS3BP as one of the top five candidate biomarkers." (PMID 39432076, 2024). "Both IFN-α and IFN-γ were found to increase LGALS3BP mRNA expression and secretion in ovarian carcinoma cell lines, whereas other treatments, such as IL-1β and TNF-α, did not consistently affect LGALS3BP secretion." (PMID 39432076, 2024). "In a study involving 73 ovarian cancer patients and 70 patients with benign gynecological conditions, elevated serum levels of LGALS3BP and CA125 were observed." (PMID 39432076, 2024). "Adhesion to LGALS3BP has been documented as a mechanism for drug resistance in lymphoma, lung cancer and ovarian cancer." (PMID 37032358, 2023). "Literature indicates some potential examples in sEVs, e.g. in a study in ovarian cancer-derived vesicles galectin-3-binding protein (LGAL3BP), was previously identified as a sialoprotein." (PMID 35784319, 2022). "Evidence was provided that both IFN-α and IFN-γ upregulate the level of mRNA expression and the secretion of LGALS3BP in 3 ovarian carcinoma cell lines." (PMID 34565385, 2021). "It’s finally to be noted that the presence of LGALS3BP int the compartment of cancer-derived extracellular vesicles (EV)s was for the first time identified in ovarian cancer." (PMID 34565385, 2021). "In the same study, the galactoside-binding soluble 3 binding protein (LGALS3BP) was identified in most of the EV samples, which is in line with the previous reports of the presence of LGALS3BP in uveal melanoma and ovarian cancer EVs." (PMID 33430152, 2021). "Subsequently, the top five candidate biomarkers, including LGALS3BP were validated by immunohistochemistry on TMAs (Tissue MicroArrays) and survival analyses in a large series of > 200 primary early stage ovarian cancer tissues." (PMID 34565385, 2021). "LGALS3BP was identified as an Exosomal marker from SKOV-3 ovarian carcinoma cells and N-glycans from the exosomes were characterised." (PMID 29262670, 2017). "The up regulation of CLIC1 and LGALS3BP in ovarian cancer tissues in quantitative proteomics were verified by western blotting and immunohistochemistry." (PMID 27825122, 2016). "CLIC1 and LGALS3BP were strongly expressed in 13 ovarian cancer tissues compared with normal ovary tissues by immunohistochemistry." (PMID 27825122, 2016). "By using immunohistochemistry and western blotting, we confirmed LGALS3BP was up regulated in ovarian cancer, which was consistent with our quantitative proteomics results and previous reports." (PMID 27825122, 2016). "High levels of CLIC1 in ovarian cancer tumor cell cytoplasm and membrane were observed, as well as high levels of LGALS3BP in tumor cell membrane." (PMID 27825122, 2016). "Here, we found that the sialoglycoprotein galectin-3-binding-protein was an abundant component of OVMz EVs as it was found in EVs from ovarian carcinoma SKOV3 cells." (PMID 26248080, 2015). "In the present work, we have identified the sialoglycoprotein LGALS3BP as an exosome marker from ovarian carcinoma cells and we also characterized the N-glycans from exosomes." (PMID 24302979, 2013).
ovarian carcinoma (continued). "In summary, we have identified sialoglycoproteins from the exosomes of ovarian carcinoma cells most relevant being LGALS3BP that constitutes an exosome marker sialoglycoprotein." (PMID 24302979, 2013). "There are several studies demonstrating the prognostic relevance of LGALS3BP in ovarian cancer." (PMID 34565385, 2021). "The expression levels of chloride intracellular channel protein 1 (CLIC1) and lectin galactoside-binding soluble 3 binding protein (LGALS3BP) in epithelial ovarian cancer tissues were significantly higher than those in normal ovary tissues as confirmed by western blotting and immunohistochemistry." (PMID 27825122, 2016). "The up-regulation of two proteins, chloride intracellular channel protein 1 (CLIC1) and lectin galactoside-binding soluble 3 binding protein (LGALS3BP), were found in ovarian cancer tissues by quantitative proteomics and confirmed by immunohistochemistry and western blotting." (PMID 27825122, 2016). "Additionally, a link between LGALS3BP and interferons (IFNs) was established in ovarian cancer." (PMID 39432076, 2024). "Furthermore, the sialoglycoprotein galectin-3-binding protein (LGALS3BP, encoded by the LGALS3BP gene, and also known as MAC2BP), which was previously identified as an EVs marker in ovarian carcinoma SKOV3 cells was also found strongly enriched in EVs from OVMz cells." (PMID 26248080, 2015). "LGALS3BP expression is correlated with tumor differentiation grade and recurrent disease during chemotherapy, suggesting the potential use of LGALS3BP and CA125 for ovarian cancer detection and monitoring." (PMID 39432076, 2024). "Some proteins located in the cell membrane or secreted out of cell were up regulated in ovarian cancer, such as CLIC1 and LGALS3BP." (PMID 27825122, 2016). "Another report showed that release of LGALS3BP was significantly increased by treatment with IFN-γ in ovarian cancer cells, while neither IL-1β (Interleukin-1β) nor TNF-α treatment consistently influenced the secretion of LGALS3BP." (PMID 34565385, 2021). "First, serum levels of LGALS3BP and CA125 (Cancer Antigen 125) were found to be elevated in 73 ovarian cancer patients and 70 patients with benign gynecological conditions, respectively, and the sensitivity increased to 86% when a combination of the two markers was used." (PMID 34565385, 2021). "The results revealed a statistically significant high level of these two proteins in ovarian cancer tissues compared with normal control (p<0.005 and p<0.001), indicating CLIC1 or LGALS3BP may accelerate the development of tumor." (PMID 27825122, 2016). "CLIC1 and LGALS3BP were knocked down by shRAN separately in A2780 cells, but unfortunately the knockdown of LGALS3BP in ovarian cancer cells showed no significant phenotypes." (PMID 27825122, 2016). "But unfortunately, the ovarian cancer cell line with LGALS3BP knockdown shows no significant phenotype in our study." (PMID 27825122, 2016). "Taken together, LGALS3BP and CLIC1 were up regulated in ovarian cancer patients." (PMID 27825122, 2016). "Supporting the presence of LGALS3BP in other cell lines was our previous observation of a strong MAL-binding glycoprotein at approximately 100 kDa in crude exosomes of ovarian carcinoma GG and m130 cells (data not shown), or H4 neuroglioma and HEK293 cells." (PMID 24302979, 2013). "Moreover, connection between LGALS3BP and IFN was confirmed also in ovarian cancer." (PMID 34565385, 2021). "Also, the positive expression rate of LGALS3BP in ovarian cancer tissues was significant higher than in normal ovary tissues (76.9% vs. 7.7%, p<0.001)." (PMID 27825122, 2016).
colon carcinoma (11 papers, 2014 to 2025). "LGALS3BP has anti-tumor activity in colon cancer by suppressing Wnt signaling and also plays a role in preventing and treating inflammatory diseases by suppressing TAK1-dependent NF-κB activation." (PMID 39962271, 2025). "But in colon cancer, different from previous studies, LGALS3BP suppresses tumor proliferation in colon cancer cells, high expression of LGALS3BP have a good prognosis." (PMID 34760348, 2021). "Secreted LGALS3BP can inhibit colon cancer progression through binding to CD9/CD82, which suppresses Wnt/beta-catenin signaling via an ISG15-dependent proteasomal-ubiquitination mechanism." (PMID 27626310, 2016). "The authors also found that LGALS3BP knockdown resulted in increased tumor growth and metastasis formation in a syngeneic mouse colon tumor model." (PMID 26219351, 2015). "Silencing of LGALS3BP in HCT-116 human colon cancer cells resulted in enhanced β-catenin expression that was reversed by addition of human recombinant LGALS3BP." (PMID 26219351, 2015). "Despite the findings regarding the functions of Lgals3bp in colon cancer, its precise role in colon inflammation and tumorigenesis is unknown." (PMID 33824294, 2021). "Importantly, recombinant LGALS3BP was demonstrated to inhibit neutrophil activation and siRNA-mediated reduction of LGALS3BP expression in HT-29 colon cancer cells increased neutrophil-induced apoptosis of the HT-29 cells." (PMID 34966391, 2021). "Therefore, Lgals3bp induction is a therapeutic option for colon cancer." (PMID 33824294, 2021). "Hence, they speculated that the relative ratio between LGALS3BP and galectin-3 secreted by colon cancer cells in vivo may play an important role during colon cancer progression and metastasis by modulating tumor cell adhesion." (PMID 34565385, 2021). "Therefore, the Lgals3bp-mediated negative regulation of TAK1 might be a key target for colon cancer immunotherapy." (PMID 33824294, 2021). "Role and significance of LGALS3BP in colon carcinoma is more controversial, as some studies have been published showing data in support of the hypothesis that in this contest the protein has tumor promoting properties and others demonstrating antitumoral mechanisms of LGALS3BP." (PMID 34565385, 2021). "Here, we revealed that Lgals3bp is an endogenous negative regulator of TAK1 in the colon and suggest that Lgals3bp induction or use of the Lgals3bp-based peptide might be a potential therapeutic approach for IBD and colon cancer." (PMID 33824294, 2021).
COVID-19 (11 papers, 2020 to 2024). A disease caused by infection with severe acute respiratory syndrome coronavirus 2. "Here, we analyzed the expression of 90K/LGALS3BP in 44 hospitalized COVID-19 patients at multiple levels." (PMID 37162650, 2023). "Mining of published PBMC scRNA-seq datasets uncovered monocyte-specific induction of LGALS3BP mRNA expression in COVID-19 patients." (PMID 37162650, 2023). "In summary, in our cohort of SARS-CoV-2-infected individuals, 90K protein concentrations were enhanced in sera and reduced in PBMCs, while LGALS3BP mRNA expression in PBMCs from COVID-19 patients remained unaltered as compared to healthy controls." (PMID 37162650, 2023). "Complementary, we analyzed two single cell RNA-sequencing datasets for expression of LGALS3BP in respiratory specimens and PBMCs from COVID-19 patients." (PMID 37162650, 2023). "The elevation of IL-6 and TNF-α was shown to be associated with the severity of COVID-19 due to the cytokine storms, and remarkable elevation of plasma LGALS3BP was also observed in COVID-19 ICU patients." (PMID 35958562, 2022). "Of the proteins revealed to bind spike, only LGALS3BP and members of the complement cascade were also specifically elevated in COVID-19 ICU patients." (PMID 34099652, 2021). "LGALS3BP abundance in COVID-19 patients closely correlated with proteins and regulators of the complement cascade (C6, C9, C4BPA, and C4BPB)." (PMID 34099652, 2021). "Apart from apolipoprotein D (APOD), LGALS3BP was the only protein to be retrieved to a greater extent with spike glycoprotein from plasma of COVID-19 ICU patients compared to COVID-19-negative plasma." (PMID 34099652, 2021). "As for IRF9, according to COVID-19-related studies, similar with LGALS3BP, this gene is typically expressed in multiple respiratory infection diseases." (PMID 33505977, 2020). "In summary, our study describes the expression pattern of LGALS3BP in COVID-19 at multiple levels." (PMID 37162650, 2023). "To identify potential cell type-specific LGALS3BP mRNA expression patterns in individual cell types of PBMCs of COVID-19 patients that may be undetectable in our whole-PBMC analysis, we analyzed published scRNA-seq datasets from a Dual Center Cohort Study." (PMID 37162650, 2023). "Notably, we likewise measured increased levels of Lgals3bp protein in lungs, which was shown to be regulated also in plasma of COVID-19 patients and correlated with severity." (PMID 34381043, 2021). "In our previous work, we identified galectin-3 binding protein (LGALS3BP), as well as ApoD, as interactors of the spike through immunoprecipitation-MS of plasma of patients with COVID-19 supplemented with recombinant spike protein." (PMID 37343697, 2023). "Since LGALS3BP is an ISG, enhanced 90K serum levels in patients with severe COVID-19 could possibly reflect exaggerated type I IFN responses." (PMID 37162650, 2023). "PBMCs of our COVID-19 cohort (19 samples from n = 14 individuals) showed no upregulated LGALS3BP mRNA expression compared to healthy controls and no time-dependent expression changes, as judged by qRT-PCR analysis in bulk PBMCs." (PMID 37162650, 2023). "Strikingly, scRNA-seq data from respiratory samples of COVID-19 patients showed no upregulated LGALS3BP mRNA expression, illustrating the multifaceted ability of SARS-CoV-2 to antagonize or evade cellular sensing machineries in productively infected cells." (PMID 37162650, 2023). "In our proteomics study, Gal-9 was not identified, but in accordance with these results, the Galectin-3-binding protein (Gal-3BP) with a role in innate immune response to viruses was significantly overrepresented in all symptomatic COVID-19 cohorts." (PMID 34566994, 2021). "Interestingly, we identified low to absent LGALS3BP expression levels in CD163hi and HLA-DRlo S100Ahi monocytes of cohort A in severe COVID-19 while patients with mild COVID-19 showed elevated levels compared to controls." (PMID 37162650, 2023).
COVID-19 (continued). "However, Galectin-3 binding protein was recently identified as elevated in critically ill COVID-19 patients only (and not in disease controls) and to correlate with complement proteins and regulators." (PMID 36203596, 2022). "LGALS3BP was markedly elevated in COVID-19 patients as discovered by DIA-MS and confirmed by ELISA, but unchanged between control and sepsis patients without COVID-19." (PMID 34099652, 2021).
prostate carcinoma (11 papers, 2013 to 2025). A carcinoma that arises from epithelial cells of the prostate gland. "There are significant differences in the expression of LGALS3BP in prostate cancer, and some research reports have shown that high LGALS3BP promotes the occurrence, proliferation, differentiation and metastasis of cancer cells." (PMID 38393692, 2024). "LGALS3BP has earlier been shown to be upregulated in human colorectal and prostate cancer which may influence oncogenesis and promote cancer growth and angiogenesis through the PI3K/AKT/VEGFA pathway." (PMID 36497496, 2022). "Interestingly, among these markers, LGALS3BP resulted to be the most significant differential expressed in prostate cancer samples." (PMID 34565385, 2021). "Our study revealed an important prostasome in the ROS- group, the Galectin-3 binding protein (LGALS3BP) which could represent an important candidate biomarker of reproduction and prostate cancer." (PMID 24004880, 2013). "Therefore, the abnormal expression of CD33 and LGALS3BP might have collaboratively facilitated the development of prostate cancer and immune evasion." (PMID 38888513, 2024). "Results obtained from this study showed that LGALS3BP was mostly lost in PIN (prostatic intraepithelial neoplasia), while it was overexpressed in 38.4% of analyzed prostate cancer tumor samples." (PMID 34565385, 2021). "Moreover, using LNCaP cell model researcher suggested that LGALS3BP induced IL-6 release which, in turn upregulated promatrilysin (pro-MMP-7), a matrix metalloproteinase responsible of degradation of many ECM (Extracellular Matrix) proteins and whose expression is crucial in prostate cancer." (PMID 34565385, 2021).
endometrial cancer (10 papers, 2010 to 2025). Primary or metastatic malignant neoplasm involving the endometrium (mucous membrane that lines the endometrial cavity). "As part of this study, LGALS3BP was found to be enriched in circulating EVs isolated from endometrial cancer patients with a high risk of recurrence." (PMID 34565385, 2021). "Levels of extracellular vesicles, LGALS3BP (galectin 3 binding protein), miR-15a-5p, and miR-21–3p were elevated, while levels of miR-26a-5p, miR-130a-3p, miR-139, miR-219a-5p, miR-222–3p, and miR-885 were decreased in endometrial cancer cases versus controls." (PMID 40987065, 2025). "Only one of these proteins, LGALS3BP (galectin 3 binding protein), was consistently reported across multiple independent studies to be elevated in endometrial cancer cases versus controls." (PMID 40987065, 2025). "Levels of extracellular vesicles, LGALS3BP, miR-15a-5p and miR-21–3p were elevated and miR-26a-5p, miR-130a-3p, miR-139, miR-219a-5p, miR-222–3p and miR-885 were decreased in endometrial cancer cases versus controls." (PMID 40987065, 2025). "Galectin-3-binding protein (LG3BP) was significantly increased in endometrial cancer cases and showed promise as an endometrial cancer diagnostic biomarker." (PMID 38513301, 2024). "Further data suggesting a LGALS3BP role in cancer-derived EVs were obtained in endometrial cancer (EC)." (PMID 34565385, 2021). "LGALS3BP has been found to stimulate host defenses and is elevated in individuals with various types of cancer such as breast, lung, colorectal, ovary, and endometrial cancers, many of which are obesity-related." (PMID 28095459, 2017). "The LGALS3BP is a 90-kD protein, designated serum protein 90 K that was found at elevated concentrations in the serum of patients with various types of breast, lung, colorectal, ovarian, and endometrial cancer." (PMID 20540791, 2010). "It was demonstrated that upon LGALS3BP overexpression, the PI3K/AKT/VEGFA signaling pathway was activated, significantly promoting the proliferation and migration of endometrial cancer cells." (PMID 39434140, 2024). "It therefore appears that levels of extracellular vesicles and LGALS3BP are general markers of cancer and may not be suitable as specific biomarkers for endometrial cancer." (PMID 40987065, 2025).
pancreatic cancer (10 papers, 2018 to 2025). "Subsequent studies focused on N-glycosylation profile of LGALS3BP in pancreatic cancer using proteomic approaches." (PMID 34565385, 2021). "Although LGALS3BP has been studied as a putative prognostic factor in pancreatic cancer, little about its biological functions in conferring cancer stemness properties is known." (PMID 32503348, 2020). "LGALS3BP, a multifunctional glycoprotein involved in immunity and cancer, has seven consensus N-glycosites, and has been found heavily glycosylated in the tumor tissue and blood from pancreatic cancer patients." (PMID 35897829, 2022). "The analysis lead to the identification of TIMP-1, FN-1, SPARC, IGFBP-3, LGALS3BP, and GREM1 as the most upregulated glycoproteins in early-stage pancreatic tumor tissues as compared to controls." (PMID 40345589, 2025). "This study presented a set of glycoproteins having aberrant N-glycosylation levels in pancreatic cancer, including mucin-5AC (MUC5AC), carcinoembryonic antigen-related cell adhesion molecule 5 (CEACAM5), insulin-like growth factor binding protein (IGFBP3), and galectin-3-binding protein (LGALS3BP)." (PMID 33672926, 2021). "Interestingly N-glycosilation levels were increased in pancreatic cancer samples,] from proteins such as mucin-5AC (MUC5AC), carcinoembryonic antigen-related cell adhesion molecule 5 (CEACAM5), insulin-like growth factor binding protein 3 (IGFBP3) and galectin-3 binding protein (LGALS3BP)." (PMID 31349663, 2019).